FLYWCH1 (FLYWCH-type zinc finger 1)
Description:
Transcription cofactor. Negatively regulates transcription activation by catenin beta-1 CTNNB1, perhaps acting by competing with TCF4 for CTNNB1 binding. May play a role in DNA-damage response signaling. Binds specifically to DNA sequences at peri-centromeric chromatin loci.
Synonyms: DKFZp761A132
Tractability: PROTAC: UniProt records ubiquitination sites on it; ubiquitination databases record sites on it.
Gene: Protein-coding gene on chromosome 16 (2,911,599 to 2,951,208, forward strand). Ensembl gene ENSG00000059122.
Subcellular location: Nucleus; Chromosome, centromere
Subcellular location (Human Protein Atlas): Nuclear bodies; Nucleoplasm; Cytosol
Gene Ontology:
Molecular function: protein binding; transcription coactivator binding; transcription corepressor activity
Biological process: DNA damage response; negative regulation of transcription by RNA polymerase II
Cellular component: nuclear body; nucleoplasm; nucleus; pericentric heterochromatin; transcription regulator complex; chromosome, centromeric region
Genetic constraint (gnomAD): Loss-of-function variants: 77 observed, 56.51 expected, observed/expected ratio (o/e) 1.36, 90% interval 1.13 to 1.65. The synonymous counts are far from expectation, so gnomAD's model fits this gene poorly and the ratio says little. Missense variants: 1,303 observed, 917.55 expected, observed/expected ratio (o/e) 1.42, 90% interval 1.36 to 1.49. Synonymous variants: 586 observed, 379.83 expected, observed/expected ratio (o/e) 1.54, 90% interval 1.44 to 1.65.
Homologues: Orthologues: chimpanzee FLYWCH1 (99% identical), macaque FLYWCH1 (91% identical), guinea pig FLYWCH1 (72% identical), rat Flywch1 (66% identical), mouse Flywch1 (65% identical). Paralogues in human: FLYWCH2 (11% identical).
Diseases named in the same sentence as FLYWCH1 in open-access papers:
FLYWCH1 is named in the same sentence as 10 diseases in open-access papers, as found by Europe PMC text mining. Sharing a sentence is not in itself a finding about the gene and the disease. The quoted sentences say what the papers report.
colorectal cancer (2 papers, 2021 to 2025). A primary or metastatic malignant neoplasm that affects the colon or rectum. "In human colorectal cancer, FLYWCH1 acts as a novel repressor of Wnt/β-catenin signaling, by which it regulates cell polarity and migration." (PMID 40672334, 2025). "More recently, we showed that overexpression of FLYWCH1 reduces the motility and increases cell attachment in colorectal cancer (CRC) cells via modulating Wnt/β-catenin signaling." (PMID 33924684, 2021). "We found that FLYWCH1 colocalises with γH2AX in normal fibroblasts and colorectal cancer (CRC) cell lines." (PMID 33924684, 2021).
coronary artery disease (1 paper, 2023). "Flywch1 was found to be a master regulatory gene in coronary artery disease and affected cholesterol-ester accumulation in foam cells." (PMID 36839306, 2023).
epithelial ovarian cancer (1 paper, 2025). "This is in line with previous studies that found that c-Myc is negatively correlated with FLYWCH1 expression and that c-Myc is an important factor in ovarian cancers as it is upregulated in platinum resistant cells and associated with decreased disease-free and OS." (PMID 40191655, 2025).
familial mitral valve prolapse (1 paper, 2021). An instance of mitral valve prolapse (disease) that is caused by an inherited modification of the individual's genome. "Another study also suggested that mutation variants in FLYWCH1 might be deleterious and associated with familial mitral valve prolapse (MVP) in humans, implying the alteration of the FLYWCH1 gene expression in the cardiovascular system." (PMID 33924684, 2021).
cancer (4 papers, 2020 to 2025). A tumor composed of atypical neoplastic, often pleomorphic cells that invade other tissues. "The first publication that focused on FLYWCH1 in cancer postulated that FLYWCH1 directly binds to nuclear β-catenin and thereby inhibits canonical wingless and int- 1 (Wnt) signalling." (PMID 40191655, 2025). "So far, the general function of FLYWCH1 and its role in cancer biology is not fully understood." (PMID 40191655, 2025). "Nevertheless, undoubtedly, the functions and regulation of FLYWCH1, particularly in cancer, could be modulated through multiple signalling pathways and are not restricted to Wnt signalling." (PMID 33924684, 2021). "Unexpectedly, apart from the colocalisation with γH2AX, an upregulation of γH2AX was noticed in FLYWCH1-expressed cells (GFP+) in both normal and cancer cell lines." (PMID 33924684, 2021).
tumours (1 paper, 2025). "This is in line with earlier findings that loss of FLYWCH1 induces tumour progression of CRC and AML, suggesting that it is indeed an important player in tumour progression." (PMID 40191655, 2025). "This suggests not only a tumour suppressive role for FLYWCH1 in CRC but also its potential as a biomarker for or therapeutic target against metastatic CRC." (PMID 40191655, 2025).
FLYWCH1 also shares sentences with these, for which no sentence is quoted: atherosclerosis (1 paper); inflammatory bowel disease (1); mitral valve prolapse (1); ovarian cancer (1).